SNORD54 (small nucleolar RNA, C/D box 54)
Synonyms: U54; RNU54
Gene: Small nucleolar RNA gene on chromosome 8 (56,073,835 to 56,073,901, reverse strand). Ensembl gene ENSG00000238650.
Gene Ontology:
Biological process: RNA processing
Cellular component: nucleolus
Homologues: Orthologues: macaque SNORD54 (94% identical), guinea pig SNORD54 (87% identical), rabbit SNORD54 (85% identical), rat Snord54 (85% identical), mouse Gm24016 (81% identical), pig SNORD54 (79% identical), tropical clawed frog SNORD54 (66% identical), zebrafish SNORD54 (60% identical).
Diseases named in the same sentence as SNORD54 in open-access papers:
SNORD54 is named in the same sentence as 2 diseases in open-access papers, as found by Europe PMC text mining. Sharing a sentence is not in itself a finding about the gene and the disease.
SNORD54 shares sentences with these, for which no sentence is quoted: autism spectrum disorder (1 paper); infection (1).